TLR4 (toll like receptor 4)
Diseases named in the same sentence as TLR4 in open-access papers (continued):
Sharing a sentence is not in itself a finding about the gene and the disease.
breast cancer (continued). "For example, the upregulation of TLR-4 and PPAR-α expression is related to breast cancer cell apoptosis." (PMID 33536908, 2020). "To study the role of TLR4/NF-κB pathway in breast cancer, we assessed the expression of TLR4 and NF-κB in normal breast tissues and different TNM-stages breast cancer tissues using tissue microarray and immunohistochemistry technology." (PMID 33363472, 2020). "The results indicated that TLR4, MyD88 and p-NF-κB p65 were up-regulated in NMU-induced breast cancer, along with its downstream pro-inflammatory factors." (PMID 33363472, 2020). "Results of the Western blot analysis showed that the CV extract decreased the LPS-induced activation of TLR4 both in HUVEC endothelial cells (p < 0.05) and MCF-7 breast cancer cells (p < 0.05)." (PMID 33260615, 2020). "We also found that exosomes secreted by the breast cancer cell line MDA-MB-231, expressed TGF-β1 at a very low level, as compared to exosomes released by the other cells lines, even after TLR4 cell activation, and fail to induce regulatory T cells." (PMID 31186484, 2019). "Caffeic acid phenethyl ester can down-regulate TLR4, MyD88, IRAK4, TRIF and NF-κB p65 expression, induce cell apoptosis, and induce autophagy during the process in LPS-induced breast cancer cells." (PMID 30213077, 2018). "Our results suggested that Chinese propolis and its major constituent – CAPE inhibited TLR4 signaling pathway molecules such as TLR4, MyD88, IRAK4, TRIF and NF- kB p65, which might be one of the major causes for Chinese propolis and CAPE to inhibit breast cancer cell proliferation and survive." (PMID 28950845, 2017). "In our study, it seems that treatment of LPS, a ligand of TLR4, increased TLR4 expression, thereby promoting MCF7 breast cancer cell migration or invasion." (PMID 28212583, 2017). "In the present study, M13SV1-EGFP-Neo human breast epithelial cells, MDA-MB-435-Hyg human breast cancer cells and two hybrids M13MDA435-1 and -3 were investigated for TLR4 and TLR9 expression and signaling." (PMID 27187369, 2016). "In accordance to recently published data MDA-MB-435-Hyg human breast cancer cells and M13MDA435-1 and -3 hybrid cells exhibited comparable expression levels of TLR4, TLR9, TRIF, Myd88, and TRAF6." (PMID 27187369, 2016). "In the present study the role of TLR4 signaling in human M13SV1-EGFP-Neo breast epithelial cells, human MDA-MB-435-Hyg breast cancer cells and M13MDA453 hybrid cell lines was investigated." (PMID 26863029, 2016). "The most common HFD used in research is lard-based, which contains high levels of saturated fatty acids, known activators of the toll like receptor 4 (TLR4) pathway, a contributor to breast cancer." (PMID 27042159, 2016). "Apart from MDA-MB-468, the TN breast cancer cells were also demonstrated to express the co-receptors CD14 and MD2 meaning that they harbor the necessary proteins for a functional TLR4 signal to occur." (PMID 26392082, 2015). "Expression of TLR4 on MCF-7 and MDA-MB-231 human breast cancer cell lines was analyzed by RT-PCR, real time-PCR, flow cytometry and western blotting." (PMID 25299052, 2014). "There was also an increase in the expression of TLR4 by mononuclear inflammatory cells and TLR9 by fibroblast-like cells in mammary tumors." (PMID 24904578, 2014). "Our results identified that TLR4 and MyD88 was expressed in MCF-7 and MDA-MB-231 human breast cancer cells, and the expression of TLR4 and MyD88 in both cell lines was increased notably is response to LPS stimulation and reduced by antagonist eritoran." (PMID 25299052, 2014). "Because several studies have compared IDC and other types of breast carcinomas in Chinese women, we included only IDC in our study and focused on the clinical significance of TLR4-MyD88 markers in IDC." (PMID 25360699, 2014). "Samples of mammary carcinomas with recurrence have also exhibited a significant increase in the mRNA levels of TLR3, TLR4, and TLR9." (PMID 22295250, 2012).
breast cancer (continued). "The purpose of the present study was to investigate the expression of TLR3, TLR4 and TLR9 in breast cancer as well as its relation to distant metastasis." (PMID 21129170, 2010). "The expression levels of TLR3, TLR4 and TLR9 were analyzed on tumors from 74 patients with breast cancer." (PMID 21129170, 2010). "The expression levels of TLR3, TLR4 and TLR9 have clinical interest as indicators of tumor aggressiveness in breast cancer." (PMID 21129170, 2010). "Breast cancer cells exhibit high surface expression of heparan sulfate (HS) and chondroitin sulfate glycosaminoglycan (CSG), which act as endogenous ligands to specifically activate Toll-like receptor 4 (TLR4) on TANs." (PMID 40568594, 2025). "TLR4 expression was an independent prognostic indicator of DFS in breast cancer patients, but not related to OS." (PMID 38463226, 2024). "explored the impact of exercise on monocyte function in breast cancer survivors, revealing that acute aerobic exercise downregulates TLR2 and TLR4 expression on monocytes and attenuates intracellular pro-inflammatory cytokine production, although the precise molecular mechanisms remain elusive." (PMID 38903515, 2024). "The TLR4 agonist, high mobility group box 1 (HMGB1), might be involved because it was largely elevated in bevacizumab-resistant breast cancer." (PMID 37108657, 2023). "In breast cancer, on the one hand, miR-182 targets and regulates the expression of CD3D, IL-2-inducible tyrosine kinase (ITK), FOXO1, nuclear factor of activated T cells (NFATs), TGFβ, and Toll-like receptor 4 (TLR4) to promote progression." (PMID 37174715, 2023). "We showed previously that MMTV-PyMT mammary tumors may originate from mammary alveolar LPs, which express TLR pathway genes (e.g., Tlr4, Cd14, Lbp)." (PMID 36765715, 2023). "Furthermore, TLR4 has been found to be overexpressed in breast cancer tissue and is the most highly expressed member of the TLR family in MDA-MB-231 breast cancer cells." (PMID 37371732, 2023). "Overall, EPS has differential activity on breast cancer cells that does not require TLR4, unlike previous studies showing that TLR4 signaling is required on myeloid cells for the anti-inflammatory effect of EPS." (PMID 38074643, 2023). "Furthermore, S100A7 overexpression downregulated TLR4 and upregulated RAGE expression in breast cancer cells." (PMID 33969603, 2022). "The previous studies showed that clinical use of proinflammatory markers (TLR2, TLR2, TLR4, TNF-α, sTNFR-1, and sTNFR-2) provided a means of evaluating inflammatory diseases such as inflammatory bowel disease, breast cancer, coronary artery disease, chronic heart failure, and type 2 diabetes." (PMID 35425840, 2022). "Whereas mammary tumor growth was not significantly affected by TLR4 inhibition, both the size and number of metastatic nodules were reduced by TLR4i." (PMID 35469015, 2022). "However, the mechanism of RGZ in breast cancer angiogenesis that targets PPARγ, HIF, TLR4, and AMPK signaling pathways needs to be clarified." (PMID 36114448, 2022). "Next, we evaluated the direct effect of LPS treatment on the expression of TLR4 in the presence or absence of S100A7 in breast cancer cells." (PMID 33969603, 2022). "TLR4 and TLR7 also correlated with a significantly poorer prognosis in the MetastaSys cohort, as previously demonstrated for breast cancer primaries." (PMID 36224342, 2022). "In breast cancer, autophagy induced high-mobility group box 1 (HMGB1) secretion from CAFs further mediates CAF-CSC interaction and promotes tumorigenesis and therapeutic resistance in a Toll-like receptor 4 (TLR4)-dependent pattern." (PMID 35488263, 2022). "Therefore, the basal subtype is the only intrinsic molecular subtype of breast cancer, which showed an inverse pattern of expression for S100A7 and TLR4 as compared to normal samples." (PMID 33969603, 2022). "The macrophage migration inhibitory factor could induce breast cancer cell migration and metastasis via HMGB1/TLR4/NF-κB activation." (PMID 35610613, 2022).
breast cancer (continued). "Our results are further supported by the previously proposed mechanism involving Toll-like receptor 4 (TLR4), overexpressed in breast cancer patients with lymph node metastasis, that was induced in both ET-treated human breast cancer cells, MCF-7 and MDA-MB-231, resulting in increased invasiveness." (PMID 34868543, 2021). "TLR4 is the most expressed among the TLR family, on breast cancer cells (MDA-MB-231 cells)." (PMID 33747948, 2021). "Furthermore, we found that the expression of TLR4 and NF-κB in high TNM stages was significantly higher than that in low TNM-stages of breast cancer." (PMID 33363472, 2020). "Similarly, LPS stimulation of breast cancer (BC) cell lines MCF-7 and MDA-MB-231 induce metastasis by activating TLR4." (PMID 32806665, 2020). "Based on these results, we deduced that TLR4 signaling pathway might be the target molecule for Chinese propolis and CAPE to inhibit breast cancer cell proliferation in inflammatory-mediated tumor microenvironment." (PMID 28950845, 2017). "Meanwhile, TLR4 RNA expression in breast cancer with node metastasis is much higher than that without node metastasis." (PMID 29029545, 2017). "Analysis of members of the TLR4 signal transduction cascade revealed comparable expression levels of Myd88 and TRAF6 in MDA-MB-435-Hyg breast cancer cells and M13MDA435 hybrid cells, whereas in M13SV1-EGFP-Neo breast epithelial cells the expression levels of these proteins were much lower." (PMID 26863029, 2016). "Moreover, TLR4 and TLR9 as well as TRIF, Myd88 and TRAF6 expression levels of MDA-MB-435-Hyg breast cancer cells were comparable to M13MDA435-1 and -3 hybrid cells." (PMID 27187369, 2016). "Among the TLRs (TLR1-10), expressed on human breast cancer cell line MDA-MB-231, expression of TLR4 was found to be the highest, and knockdown of TLR4 gene resulted in significant cell death and inhibition of IL-6 and IL-8 cytokines, compared with vector control." (PMID 24904578, 2014). "A high level of MyD88 and TLR4 protein expression was confirmed in the hormone-resistant breast cancer cell lines MDA-MB-231, MDA-MB-231HM, and MDA-MB-468 but not in the MCF-7 and SKBR3 cell lines." (PMID 25360699, 2014). "The relationship between MTDH and TLR4 signaling pathway might lead to the development of TLR4 and MTDH as novel therapeutic targets for breast cancer." (PMID 22195048, 2011). "To study the biological role of TLR4 in the progression of human breast cancer cell line MDA-MB-231, we constructed pGenesil-1 plasmid vectors expressing three different siRNAs directed against TLR4 [GenBank: NM_138554.3] to selectively reduce TLR4 gene expression in MDA-MB-231." (PMID 20618976, 2010). "Our results show high expression of TLR3, TLR4 and TLR9 by breast cancer cells though." (PMID 21129170, 2010). "Importantly, this synergistic effect is particularly pronounced in TLR4-positive MDA-MB-231 breast cancer cells, while the effect is less evident in HCC1806 cells that lack TLR4, underscoring the critical role of TLR4 in the therapeutic combination of hyperoside and paclitaxel." (PMID 40098612, 2025). "In basal-like and HER2-positive breast cancers, we demonstrated that a low WWOX/HIF1A ratio is particularly detrimental, as it triggers HIF1α-mediated upregulation of immunosuppressive mediators such as TLR4, NOTCH1, PTX3, and IL6R, alongside glycolytic enzymes like GLUT1 and HK2." (PMID 41007296, 2025). "Additionally, Previous evidence had shown thatS100A7 could interact with advanced glycosylation end product receptor (RAGE) and Toll-like receptor 4 (TLR4), thereby exerting paracrine effects and promoting the infiltration of macrophage in breast cancer." (PMID 38499391, 2024). "Moreover, FAs in the breast cancer TIME are recognized by TLR4 on the cell surface of macrophages, which activates the NF-κB signaling pathway and increases the release of pro-inflammatory factors, such as PGE2 and OSM to subsequently cause local inflammation in the TME of BC." (PMID 36765683, 2023).
breast cancer (continued). "Interestingly, S100A7 showed a significant negative correlation with TLR4 expression in the same cohort of breast cancer patient samples with their adjacent normal controls." (PMID 33969603, 2022). "Moreover, these dose-dependent effects on metastatic infiltration seem to be exclusive of the TLR4 signaling, since stimulation of other TLRs did not affect the infiltration of the breast cancer cells in our ex vivo model." (PMID 36224342, 2022). "TLR4 via MAPK and circAMOTL1 via AKT in breast cancer cells could heavily affect the cell cycle." (PMID 36132137, 2022). "Moreover, the up‐regulation of TLR3, TLR4 and TLR9 expressions could increase the probability of biochemical recurrence and cancer metastasis in prostate and breast cancer, respectively." (PMID 33336901, 2021). "Together, the TAZ/Resistin/TLR4 axis may serve as a link between adipocyte and nonautonomous breast cancer progression, and Resistin might be a therapeutic target for clinical breast cancer treatment." (PMID 33318171, 2020). "DNA methylation was quantified from d = 6, 4, or 4 CpG sites located in OPRM1, TLR4, and LINE1, respectively, in n = 70 patients with persistent pain and in n = 70 patients assigned to the “non-persistent pain” phenotype group based on the 3-year follow-up data after breast cancer surgery." (PMID 31775878, 2019). "In breast cancer cells, DHA significantly increased the ratio of cyclic adenosine monophosphate (cAMP)/cyclic guanosine monophosphate (cGMP) levels and promoted the expression of Toll-like receptor 4 (TLR-4) and peroxisome proliferator activated receptor (PPAR)-α, resulting in apoptosis." (PMID 30400136, 2018). "However, there is no knowledge about role of TOPK in LPS/TLR4-induced invasion of cancer, specifically breast cancer, cells." (PMID 28212583, 2017). "However, the level of MSC-derived monocyte chemotactic protein-1 (MCP-1), was much higher in the supernatant of TLR4+MSCs, suggesting that TLR4 may play a vital role in induction of MCP-1, which has been defined as a promoter in breast cancer cell migration." (PMID 29029545, 2017). "Based on our finding, propolis and its major component – CAPE could inhibit the proliferation and migration of the TLR4 positive breast cancer MDA-MB-231 cell line in inflammatory microenvironment by activation of apoptosis, autophagy and inhibition of TLR4 signaling pathway." (PMID 28950845, 2017). "Because of that we conclude that MDA-MB-435-Hyg breast cancer cells should possess a functional TLR4 signaling, but that the lack of expression of NF-κB target genes might be attributed to an epigenetic and/or miRNA dependent mechanism." (PMID 26863029, 2016). "Therefore, in this study, we aimed to determine which TLRs were expressed in human breast cancer cell line MDA-MB-231 and whether TLR4 played a functional role in the growth and progression of MDA-MB-231." (PMID 20618976, 2010). "Moreover, LPS–TLR4 signaling in breast-cancer cells can activate NF-κB and pro-invasive programs, while TAM-derived IL-10 sustains immunosuppression—motivating co-profiling of metabolites and MAMP pathways (e.g., TLR4 activity) when interpreting immune phenotypes or designing combinations." (PMID 41339918, 2025). "However, it is not known how SOCE affects the TLR4 signaling in breast cancer cells." (PMID 37371732, 2023). "Therefore, TLR4 has a negative impact on the prognosis of breast cancer patients, and its expression may improve the prognosis of breast cancer patients." (PMID 33138076, 2020). "This study focuses on two proteins, TLR4 and AGER, which are known to play roles in other types of breast cancer but have not been well-studied in inflammatory breast cancer." (PMID 40647480, 2025). "In this study, we evaluated the expression of TLR4 and AGER in inflammatory and non-inflammatory breast carcinoma samples, comparing the findings with clinical and histopathological data and their prognostic values." (PMID 40647480, 2025).
breast cancer (continued). "The expression of MTDH are presented at a higher levels in TLR4 positive breast cancer cells (MDA-MB-231,MCF-7,and MDA-MB-468) than that in TLR4 negative T47D cell lines after treated with LPS, suggesting the pro-tumor role of TLR4 expressed on tumor cells." (PMID 29029545, 2017). "PBMCs from breast cancer patients also exhibited increased TNF-α expression and protein production in response to PSP, an effect not abrogated by blockade of toll-like receptor 4 (TLR4), suggesting that PSP is independent of TLR4 activation." (PMID 28932226, 2017). "Therefore, we proposed that the TLR4/Tollip axis may involve fucose-containing polysaccharides-induced UPP in the down-regulation of TGFR expression and related signaling pathways in the breast cancer cells, leading to decreased cancer cell proliferation and metastasis." (PMID 27830743, 2016). "The expression of TLR4 in human breast cancer cell line MDA-MB-231 and its biological function in the development and progression of breast cancer have not been investigated." (PMID 20618976, 2010). "In addition, TLR4 overexpression was an independent prognostic indicator of DFS (HR= 1.480, 95%CI= 1.028- 2.130, p= 0.035) in breast cancer patients, but not related to OS(HR=1.730, 95%CI= 0.979-3.057, P= 0.059)." (PMID 38463226, 2024). "Due to a lack of TLR family immunohistochemical samples, only TLR3, TLR4, TLR7, and TLR8 staining results in colorectal cancer, breast cancer, prostate cancer, and normal tissue were exhibited, which were largely consistent with the previously reported mRNA expression." (PMID 35801728, 2022). "We found that in cells expressing both the TLR4 co-receptors MD2 and CD14 (MDA-MB-231 cells) TLR4-GFP was expressed in a vesicular pattern in the cytosol, whereas in breast cancer cells lacking both MD2 and CD14 (MCF-7 cells), TLR4-GFP was expressed evenly in the cytoplasm." (PMID 26392082, 2015). "Indeed, scoring of membrane TLR4 expression in breast cancer lesions did not reveal as much as that of cytoplasmic staining, and both TLR2 and TLR4 have been reported to be expressed intracellularly as well." (PMID 26392082, 2015). "However, the impact of the differential expression of TLR4 and AGER on the clinical presentations of BC, such as inflammatory breast cancer (IBC), has not yet been investigated." (PMID 40647480, 2025).